INS (insulin)
Diseases named in the same sentence as INS in open-access papers (continued):
Sharing a sentence is not in itself a finding about the gene and the disease.
atherosclerosis (continued). "NC is also linked to metabolic disorders such as CVD and atherosclerosis as well as influenced by changes in insulin levels." (PMID 36824177, 2023). "Decreased glucosylceramide synthesis has been linked to decreased atherosclerosis in mice and increased insulin sensitivity in vitro." (PMID 36030929, 2022). "EPHA6 gene is predicted to enable transmembrane-ephrin receptor activity and is found to be associated with insulin signaling and blood pressure phenotype, which are the known risk factors of atherosclerosis." (PMID 36539828, 2022). "The Insulin Resistance Atherosclerosis Study (IRAS) has revealed that higher levels of insulin sensitivity are associated with less atherosclerosis." (PMID 35966520, 2022). "V55 increased expression of Socs3 and Dab2 genes (inhibitors of cytokine signaling and NF-κB pathway), Apoe (associated to atherosclerosis control), Igf1 (encoder a protein with analogous effects to insulin) and Fgf10 (fibroblasts growth factor)." (PMID 35631379, 2022). "Specifically, polymorphisms in the two subunits that form the KATP channel regulating insulin secretion were associated with atherosclerosis measurements in these subjects, which supports the proposed link between T2DM and atherosclerosis." (PMID 36314849, 2022). "High insulin level is a well-established risk factor for atherosclerosis, whereas microvascular endothelial cells are vulnerable to insulin metabolism and growth promoting effects." (PMID 35169393, 2022). "The relationship of insulin therapy with the risk of atherosclerosis in T2D patients is still controversial." (PMID 35011813, 2021). "Extensive tibial atherosclerosis was an independent risk factor for limb loss and in insulin and non-insulin diabetics, it also associated with increased mortality." (PMID 33225841, 2021). "So far, although a number of studies have investigated the association between insulin treatment and atherosclerosis and its complications, the relationship between them have not been well established and the controversies remain to exist." (PMID 33598483, 2021). "As the metabolites of sphingolipid, ceramides are considered lipotoxic inducers of disturbed glucose homeostasis and insulin resistance and causative agents in the pathophysiology of atherosclerosis." (PMID 33937325, 2021). "It has been suggested that accelerated atherosclerosis in MetS is associated with defective insulin signaling pathways." (PMID 34054693, 2021). "ESMIRO mice have thus been an excellent tool to explore mechanisms of insulin resistance associated vascular oxidative stress and accelerated atherosclerosis." (PMID 32401607, 2020). "Against this background, we investigated the association between insulin and glucose levels with atherosclerotic plaque composition in the carotid artery in a large population-based cohort of subjects with subclinical atherosclerosis." (PMID 31958313, 2020). "This is consistent with data from the literature, suggesting significant dose-related effects between physical activity and the atherosclerosis risk factors, including insulin level." (PMID 32308675, 2020). "This study suggests that food supplements, containing full spectrum of bergamot juice components, such as BPE-C efficiently induce a combination of weight loss and insulin sensitivity effects together with a robust reduction of atherosclerosis risk." (PMID 31167512, 2019). "Increased levels of insulin have been reported to be an important risk factor for the development of atherosclerosis in the general population." (PMID 30786864, 2019). "Compared to mice with a single deficiency of FABP4 or FABP5, the combined deficiency of FABP4 and FABP5 better improves insulin sensitivity and protects against atherosclerosis and type II diabetes." (PMID 30142969, 2018). "In an insulin resistant state, the PI3K pathway is affected whereas the MAP kinase pathway is intact, which causes mitogenic effect of insulin in endothelial cells leading to atherosclerosis." (PMID 30170598, 2018).
atherosclerosis (continued). "The continuous insulin infusion with insulin pump in T1DM patients is likely to prevent atherosclerosis progression, thereby reducing the risk of cardiovascular disease." (PMID 27955676, 2016). "Abundant evidence also indicates that high concentrations of insulin can stimulate vascular smooth muscle cells (VSMCs) proliferation and migration, which are currently thought to be the direct causes of atherosclerosis." (PMID 27832775, 2016). "Many pieces of research have shown that miR-27 is involved in angiogenesis, adipogenesis, oxidative stress, insulin resistance, which are the known processes associated with atherosclerosis." (PMID 27257686, 2016). "Loss of insulin signaling in endothelial cells accelerates atherosclerosis in Apolipoprotein E-deficient (Apoe-/-) mice, and insulin receptor deficiency in macrophages increases necrotic core size in advanced atherosclerotic lesions." (PMID 25946019, 2015). "Prepubertal glucose–insulin metabolism is associated with adult cardiovascular risk and markers of atherosclerosis." (PMID 25940643, 2015). "For example, a six-year-long application of CR to a set of volunteers was reported to cause physiological changes that mirror those observed in CR mice, including lower blood cholesterol and insulin and a reduced risk of atherosclerosis." (PMID 24400080, 2014). "We aimed to explore circulating FGF-23 in association with fatness and insulin sensitivity, atherosclerosis and bone mineral density (BMD)." (PMID 23555610, 2013). "Defective insulin secretion, smaller islet mass and islet inflammation have been found in atherosclerosis-susceptible B6.ApoE-/- mice compared to atherosclerosis-resistant BALB.ApoE-/- mice (C57BL/6 and BALB/cJ respectively)." (PMID 23547749, 2013). "In presence of low androgen concentrations peripheral insulin sensitivity is reduced, blood vessels are more predisposed to atherosclerosis and, finally, osteoporosis is more common in patients with impaired testicular function." (PMID 24089610, 2013). "Because inhibition of SIRT1 is causally implicated in endothelial cell apoptosis in the atherosclerosis-prone aortic arch of high-fat diet-induced insulin resistant mice, expression and activity of SIRT1 were assessed in the aorta of atherosclerotic pigs." (PMID 23825667, 2013). "Complete loss of insulin signal in vascular endothelial cells aggravated atherosclerosis in endothelium-specific insulin receptor–deficient apolipoprotein E null mice." (PMID 24349318, 2013). "For example, inhibition of IFNγ-induced STAT1 signaling protects against atherosclerosis development and IFNγ is associated with the development of AT in obese patients and diminishes insulin signaling in human adipocytes." (PMID 22403661, 2012). "Increased plasma levels of TG and atherosclerosis are generally associated with impaired insulin action and glucose tolerance." (PMID 22662181, 2012). "and linked to atherosclerosis due to their direct effect on insulin release and regulation of the glucose substrate consumption in the endothelial cells by reducing ROS production." (PMID 22087257, 2011). "They observed a similar relationship between the use of intermediate-acting insulin with carotid intima-media thickness and concluded that the cumulative dose of insulin was a risk factor for atherosclerosis." (PMID 21978180, 2011). "Results of various prospective studies indicated that elevated plasma insulin levels cause and enhance atherosclerosis." (PMID 19419582, 2009).
atherosclerosis (continued). "This study evaluated ultrasonographically measured epicardial adipose tissue thickness (EATT) and perirenal adipose tissue thickness (PrATT) as markers of metabolic risk, insulin sensitivity, and subclinical atherosclerosis in children and adolescents with T1DM." (PMID 41597132, 2026). "Additionally, the upregulation of the bile-salt export pump (BSEP) and glycerolipid and hepatic cholesterol metabolism pathways causes insulin signaling impairment and atherosclerosis that leads to disease severity." (PMID 40365443, 2025). "In addition, hyperprolactinemia is associated with endothelial dysfunction and impaired insulin sensitivity, increased arterial stiffness, and the risk of atherosclerosis and cardiovascular events in high-risk patients." (PMID 38672089, 2024). "Despite these mixed results, the potential of GLP-1 RAs to modulate key pathways involved in HF, such as inflammation, endothelial function, and atherosclerosis, positions them as valuable tools in the broader management of cardiovascular risk in insulin-resistant patients." (PMID 39337658, 2024). "This defective triglyceride metabolism impacted the serum cholesterol level, which resulted in a significant decrease (p < 0.05) in the HDL-C and a significant increase (p < 0.01) in the LDL-C which can reinforce insulin resistance and the risk of atherosclerosis." (PMID 37674975, 2023). "α-Carotene endorses effects on adipogenesis controlling and glucose/insulin homeostasis, and its biological activities were related to anti-inflammatory response mediation, which contributes to the reduction of atherosclerosis and cardiovascular disease risk in MetS patients." (PMID 36771258, 2023). "Vascular endothelial dysfunction is one of the manifestations of changes in the arterial wall caused by metabolic abnormalities caused by insulin resistance; it is closely related to cardiovascular events and is an important early event in the pathogenesis of atherosclerosis." (PMID 35242879, 2022). "Such a defect in insulin signaling not only impairs the utilization of glucose and lipids, but also causes accelerated atherosclerosis and the development of organ complications such as hypertension, atherogenic dyslipidemia, metabolic associated fatty liver disease, and many others." (PMID 35885586, 2022). "In addition, compared with non-inflammatory macrophages, the pro-inflammatory macrophages were found to secrete more exosomes and induce insulin resistance in mature mouse embryonic fibroblasts (3T3-L1), causing impaired insulin secretion and atherosclerosis." (PMID 36176638, 2022). "With the chronic elevation of plasma glucose and insulin, advanced glycation end products and inflammation follow, which could promote atherosclerosis and cause resultant vascular resistance." (PMID 35031663, 2022). "Therefore, increased visceral adiposity is associated with proinflammatory activity, impaired insulin sensitivity, increased risk of atherosclerosis, and high morbidity and mortality in hemodialysis patients." (PMID 35268399, 2022). "However, the possibility of excessive insulinization during insulin therapy has raised concerns about the potential risk for accelerated atherosclerosis and its complications." (PMID 33598483, 2021). "Therefore, modulations in adipokines and markers related to vascular dysfunction and improved inflammatory status highlight the ability of Vitamin D supplementation to improve insulin sensitivity and decrease the risk of atherosclerosis in subjects with T2DM." (PMID 34239993, 2021). "Resistance to insulin is a condition that may enhance the incidence and spread of atherosclerosis due to its association with endothelial dysfunction, vasoconstriction, inflammation, and apoptosis." (PMID 33014469, 2020). "Additionally, we found that exenatide was associated with a more remarkable reduction in 8-OHdG, a marker of oxidative stress to DNA and increased risk of atherosclerosis, compared with insulin." (PMID 32334592, 2020).
atherosclerosis (continued). "Animal models studied were insulin-resistant which confers risk to atherosclerosis." (PMID 33292434, 2020). "In addition, miR-27 is highly associated with atherosclerosis and its processes such as lipid metabolism, oxidative stress, inflammation, angiogenesis, shear stress, adipogenesis, and insulin resistance." (PMID 33230462, 2020). "Therefore, we systematically examined the relative contributions of glycemia, insulin secretion, sensitivity, and clearance as well as classical cardiovascular risk factors for early atherosclerosis, assessed by cIMT." (PMID 33384433, 2020). "Interestingly, cadherin-13 has been implicated in vascular disease and atherosclerosis and others have found that cadherin-13 overexpression can promote insulin sensitivity while simultaneously reducing the ability to stimulate the Akt pathway." (PMID 32596266, 2020). "Indeed, changes in the concentrations of phosphocholine containing lipids have been associated with cardiometabolic alterations associated with excess liver and visceral fat such as insulin resistance and atherosclerosis." (PMID 31587110, 2019). "We suggest that this outcome may be because liraglutide is associated with potentiating insulin secretion capacity, inhibiting vascular inflammatory cytokines, and antagonizing atherosclerosis." (PMID 29636047, 2018). "Indeed, in both type 1 and type 2 diabetic patients, a high proportion of mortality is associated with CVD, where defective insulin signalling leads to endothelial dysfunction and accelerated atherosclerosis." (PMID 28899902, 2017). "A high fat diet rich in palmitic acid, a SFA, is associated with lower insulin sensitivity and it may also increase atherosclerosis parameters." (PMID 29065507, 2017). "In the periphery, vessel damage likely by gingipains may also allow bacteria to enter the circulatory system and cause transient bacteraemia that contribute to atherosclerosis and possibly insulin resistance." (PMID 29311898, 2017). "Exogenous insulin use is a potential risk factor for atherosclerosis and cancer." (PMID 27906989, 2016). "In addition, IL-6 and TNF-α can play a pivotal role in inflammation-associated disturbances in glucose and insulin metabolism, lipid homeostasis, endothelial dysfunction, and accelerated atherosclerosis." (PMID 27616738, 2016). "The manner in which the hyperinsulinemic state or the loss of insulin sensitivity might lead to increased atherosclerosis remains poorly defined." (PMID 26147990, 2015). "Insulin-treated DM was an established risk for atherosclerosis." (PMID 23807613, 2014). "Additional studies in whole animals and in humans are needed to further advance the theory that differential insulin signaling represents one important factor underlying the involvement of smooth muscle cells in atheroma plaque formation during the development of atherosclerosis." (PMID 25138792, 2014). "Because defective leptin signaling was found to modulate inflammation and atherosclerosis, we also studied the relation between low adiponectin (Adipoq) and Irak3 expression in aortic extracts of high-fat and insulin resistant LDL-receptor deficient mice characterized by high plasma leptin levels." (PMID 23620818, 2013). "Overall, the combination of higher plasma glucose and insulin use may progress atherosclerosis and subsequently increase the risk of IHD among elderly diabetic individuals." (PMID 21978180, 2011). "It is now well known that diminished insulin signaling in macrophages may cause atherosclerosis." (PMID 40141412, 2025). "Increased lipid accumulation in muscle is connected to muscle insulin resistance; in the liver, it leads to insulin resistance; in the kidney, it can cause nephropathy; and in the heart and blood vessels, it can result in reduced ventricular compliance and an increased risk of atherosclerosis." (PMID 39857794, 2025).
atherosclerosis (continued). "Insulin sensitivity, represented by TyG, and excessive accumulation of visceral adiposity, indicated by central adiposity measures, are both strongly associated with chronic inflammation, endothelial dysfunction, and atherosclerosis, all of which increase CVD risk." (PMID 39309107, 2024). "In addition, atherosclerosis may also be caused by a disruption in insulin signaling transduction among vascular intimal cells including endothelium, phagocytes, and SMC." (PMID 36814584, 2023). "We believe that HSP70-targeted interventions have the potential to regulate atherosclerosis, insulin resistance, inflammatory conditions, and other underlying pathologies of ASCVD." (PMID 37238736, 2023). "Moreover, (3S)-vestitol up-regulated the expression of Socs3 and Dab2 genes (inhibitors of cytokine signaling and the NF-κB pathway), Apoe (related to atherosclerosis control), Igf1 (encoder a protein with analogous effects to insulin) and Fgf10 (fibroblasts growth factor)." (PMID 35631379, 2022). "In this second analysis, the insulin-related pathways were more enriched in the first-level network, while in the extended network we observed strong enrichment of neuroactive ligand–receptor interaction and pathways involved in cancer and pathways associated with atherosclerosis." (PMID 36046822, 2022). "The molecular causes were impaired insulin signaling pathway through the phosphoinositol-3 kinase pathway with intact signaling through the mitogen-activated protein kinase pathway, which contributed to the accelerated occur of atherosclerosis in T2DM patients." (PMID 34400897, 2021). "We examined for associations of the brain insulin signaling measures with cerebrovascular pathology, and specifically with brain infarcts (including by size and location) and cerebral vessel pathologies including atherosclerosis, arteriolosclerosis, and amyloid angiopathy." (PMID 33858515, 2021). "While reductions of cardiovascular risk could be mediated through their anti-inflammatory properties, they could also facilitate progression of atherosclerosis (e.g. corticosteroid could increase cardiovascular risk through effects on blood pressure, lipid profile and insulin resistance)." (PMID 26978266, 2016). "In the DM-associated atherosclerosis, mitochondrial impairment could result from oxidative stress-induced accumulation of advanced glycation end products, with patterns of energy deficiency, which can be reverted by continuous insulin therapy." (PMID 23826148, 2013). "Thus, our results suggest that not exclusively "defective", but rather "modified" or "shifted" macrophage insulin signaling may cause a predisposition to foam cell formation and atherosclerosis in insulin-resistant states." (PMID 16787541, 2006). "Meanwhile, atherosclerosis can impair insulin delivery and exacerbate diabetic complications by reducing vascular perfusion." (PMID 41346708, 2026). "These mutant cells exhibit amplified IL-1β production, enhanced NLRP3-inflammasome activity, and increased chemokine signalling, thereby accelerating atherosclerosis, insulin resistance, and vascular inflammation." (PMID 41665140, 2026). "Visceral fat in particular releases pro-inflammatory cytokines and adipokines, such as adiponectin and leptin, which influence insulin sensitivity and promote inflammatory pathways in the vasculature, accelerating the progression of atherosclerosis." (PMID 41346708, 2026). "The estimated glucose disposal rate (eGDR) and the non-high-density lipoprotein cholesterol to high-density lipoprotein cholesterol ratio (NHHR) are effective indicators for assessing insulin sensitivity and the degree of atherosclerosis, respectively." (PMID 42292215, 2026). "The connection between MASLD and atherosclerosis is complex, with links to severe lipotoxicity, inflammation, and hepatic insulin resistance." (PMID 40431398, 2025).